RNU6-673P (RNA, U6 small nuclear 673, pseudogene)
Gene: Small nuclear RNA gene on chromosome 10 (76,260,800 to 76,260,903, reverse strand). Ensembl gene ENSG00000201954.
Homologues: Orthologues: chimpanzee U6 (100% identical), macaque U6 (97% identical), guinea pig U6 (81% identical), mouse Gm22259 (81% identical), pig U6 (76% identical), rabbit U6 (74% identical), dog U6 (69% identical). Paralogues in human: RNU6-641P (83% identical), RNU6-1263P (82% identical), RNU6-140P (82% identical), RNU6-21P (82% identical), RNU6-455P (82% identical), RNU6-549P (82% identical), RNU6-686P (82% identical), RNU6-20P (81% identical), RNU6-457P (81% identical), RNU6-463P (81% identical), RNU6-46P (81% identical), RNU6-657P (81% identical), and 1287 more.